TLR4 (toll like receptor 4)
Diseases named in the same sentence as TLR4 in open-access papers (continued):
Sharing a sentence is not in itself a finding about the gene and the disease.
viral infection (continued). "In lung tissue, TLR4 may be activated by risk factors such as smoking, inhalation of contaminated air, and bacterial and viral infections, which in turn activate NF-kB and induce the expression of inflammatory mediators." (PMID 35990849, 2022). "The role of TLR4 in viral infections could be further explored and informed by population studies of TLR4 polymorphisms." (PMID 36246240, 2022). "In the context of virus infections, TLR4 and TLR2 may also recognizes damage-associated molecular patterns (DAMPs) released during infection." (PMID 23435233, 2013). "Furthermore, it has been proposed that TLR4 activation could be beneficial for the viruses during viral infection, especially for those RNA viruses with a high mutation rate." (PMID 33138197, 2020). "The investigation of genetic variants such as the TLR4 and TLR9 polymorphisms is justified because these innate immune receptors play a critical role in the body’s first line of defense against viral infections, including HPV." (PMID 41374999, 2025). "Viral infection induces the overexpression of TLR4 and changes the organization and distribution of cytoskeleton proteins." (PMID 40573358, 2025). "Our data show that the viral infection induces an overexpression of both mRNA and surface molecule expression of TLR4." (PMID 40573358, 2025). "Compared to other feline viruses, such as FHV-1, TLR2 and TLR4 were also up-regulated at early stages (3 hpi vs. 6 hpi) of virus infection." (PMID 40872699, 2025). "Toll-like receptor 4 (TLR4) plays an important role in cell processes, the stimulation of the external environment, virus infection responses, intracellular material transport, and catabolism." (PMID 39599901, 2024). "Viral infections activate TLR4, thereby triggering subsequent cascade reactions that activate NF-κB and IFN signaling pathways." (PMID 38551978, 2024). "In virus infections or sterile inflammation, it functions as an alarmin attracting innate immune cells, as well as mediating proinflammatory effects through TLR4 signaling." (PMID 39497822, 2024). "The finding that JWH133 down-regulates TLR4 expression in dendritic cells explains the reduced resistance to well-known bacterial, protozoan and viral infections in chronic cannabinoid users." (PMID 39459513, 2024). "Calprotectin has also been suggested to increase in severe COVID-19 infection, due to the activation of TLR4 and higher neutrophil engagement compared to other viral infections." (PMID 38786153, 2024). "In these examples, glycosylated viral cell surface proteins activated TLR4, which resulted in host gene expression beneficial for the viral infection." (PMID 39450336, 2024). "Here, bLf treatment in the acute phase led to high levels of pro-inflammatory and antiviral cytokines, including high levels of TLR4, NF-κB, and downstream genes, whose activation events are pivotal for fighting against viral infections." (PMID 39483459, 2024). "Changes in the TLR4 signaling pathway as a consequence of viral infection have been already described in oral cancer." (PMID 39451550, 2024). "We are making efforts to further explore the specific mechanism by which EV71 downregulates TLR4 expression, which sheds light on the viral infection process." (PMID 38938877, 2024). "Although TLR4 is well-known for its ability to binds and respond to the LPS, its activation through virus infections has been reported." (PMID 39450336, 2024). "The seemingly unrelated concepts of TLR4 activation and virus infection have been explored for several viruses including Ebola virus, respiratory syncytial virus and Dengue virus." (PMID 39450336, 2024). "It was noticed that TLR4 is necessary for the early events of viral infection, especially during the attachment and entry stages." (PMID 37153546, 2023). "In conclusion, the current study reveals the possible regulatory role of TLR4 at the attachment as well as entry stages of viral infection via interaction with the CHIKV structural protein E2." (PMID 37153546, 2023).
viral infection (continued). "Presence of a viral infection modifies TLR4 pathways present as a reaction to pregnant women’s microbiota, and promotes a pro-inflammatory response." (PMID 37074264, 2023). "Blocking of TLR4 signaling has been suggested as a means of limiting pulmonary injury in viral infections." (PMID 36776845, 2023). "In order to understand the functional association of TLR4 with CHIKV infection, viral infection was performed in the RAW264.7 and TLR4 functional knockout TLR4KO RAW cells." (PMID 37153546, 2023). "Galectin-3 is a ß-galactoside binding lectin that can drive neutrophil chemotaxis, bind TLR4, and increase production of pro-inflammatory cytokines during viral infections." (PMID 37064248, 2023). "Activation of TLR4 by viral glycoproteins has also been observed in the context of other viral infection models, including respiratory syncytial virus (RSV), dengue virus (DENV) and Ebola virus (EBOV)." (PMID 36246240, 2022). "Further in vivo studies of EBOV and DENV infection are warranted to directly test the potential of TLR4 inhibitors as therapeutics for viral infections that result in TLR4 activation and an excessive immune response." (PMID 36246240, 2022). "While it is possible that DAMPs also contribute to TLR4 activation in the context of other viral infections, we have focused this review on the current literature implicating a specific role for viral glycoproteins in activation of TLR4." (PMID 36246240, 2022). "It is well known that a moderate activation of TLR4 by exogeneous PAMPs comprises an important mechanism of defense against viral infection in an immunocompetent host by warranting the induction of specific pro-inflammatory signaling pathways." (PMID 36678520, 2022). "pDCs produce high levels of type I IFNs in response to viral infection and other stimuli but respond to LPS moderately because they express TLR4 at lower levels than in BMDMs." (PMID 35173566, 2022). "BECCs, are a TLR4-agonist that can help drive a balanced Th1/Th2 immune response that can help clear viral infections." (PMID 35288576, 2022). "F2 was involved in the coagulation process and TLR4-mediated immune recognition against virus infection." (PMID 35165525, 2022). "TLR2 and TLR4 have also been studied to recognize the viral structural proteins, which results in the production of inflammatory cytokines against the viral infection." (PMID 36679906, 2022). "TLR4 has been previously suggested to have a role in the damaging responses that occurs during viral infections, acting via both PAMPs and DAMPs." (PMID 34030677, 2021). "Further confirmation of an alternative protective role of the TLR4 receptor was obtained from a recent study in which deprivation of TLR4 signaling worsened neurodegeneration from viral infection." (PMID 33540826, 2021). "On the other hand, dysregulated Toll-like receptor (TLR)-4 activation is involved in LPS-induced acute systemic sepsis, chronic inflammatory diseases, and in viral infections, such as influenza infection." (PMID 34200327, 2021). "The small-molecule synthetic TLR-4 antagonist, FP7, protected mice from influenza virus-induced lethality and reduced both proinflammatory cytokine gene expression in the lungs and ALI suggesting viral infection also through activating TLR-4 signaling." (PMID 34200327, 2021). "Bacterial and viral infections activate the toll-like receptor 4 (TLR4) signaling pathway, leading to an increased production of pro-inflammatory cytokines, such as nuclear factor-κB, tumor necrosis factor, interleukin (IL)-1, and IL-6." (PMID 34201172, 2021). "One proposed possibility of TLR4 activation during viral infection is the appearance of endogenous danger signals triggering TLR4, and indeed the danger signal acute phase protein 3 was heavily upregulated in productively infected astrocytes." (PMID 34696494, 2021).
viral infection (continued). "The role of TLR4 in the pathogenesis of some of these viral diseases is demonstrated by the reduced induction of cytokines and chemokines as a result of treatment with TLR4 antagonists." (PMID 33487119, 2021). "The hyporesponsiveness of liver innate immune cells to TLR4 or 7/8 stimulation is maintained in patients with a chronic viral infection, despite inflammation and activation of IFN-stimulated antiviral defense pathways." (PMID 33452360, 2021). "During the viral infection, membrane-associated proteins interaction with TLR2 and TLR4 plays a nuanced role in exceeding inflammatory responses via adhesion and invasion that vitiate the host cell (Olejnik, Hume & Muhlberger, 2018)." (PMID 33828922, 2021). "We revealed that the TLR4 inhibitor TAK significantly attenuated viral infection, judging by the observed downregulation of viral protein, viral RNA, and viral titer, as well as decreased proinflammatory cytokine production." (PMID 32340172, 2020). "Although only viral infection has been suspected as the cause of the IFN signature in SS, among the pattern recognition receptors mediating type I and III IFN induction, TLR4 and TLR9 can recognize bacterial components." (PMID 32208441, 2020). "A certain amount of TLR4-NF-κB activation benefits to the host by improving a protective immune response against viral infection." (PMID 32269560, 2020). "LNSCs enhance the expression of genes encoding inflammatory cytokines, TLR4 signaling, and MHC class II genes after LPS stimulation, viral infection, or Yersinia pseudotuberculosis infection." (PMID 33664727, 2020). "Activation of TLR4 was positively associated with activation of phosphatidylinositol-4,5-bisphosphate 3-kinase (PI3K) during some viral infections, including SARS-CoV." (PMID 33138197, 2020). "During acute viral infections, Toll-like receptor 4 (TLR4) signaling plays an important role in eliciting inflammatory responses." (PMID 33585554, 2020). "Both viral and bacterial pathogens can activate the TLR4 pathway, and modification of TLR4 signaling is reported to be involved in different viral infections including SARS-CoV as well as in LPS-induced acute lung injury." (PMID 32930095, 2020). "For instance, there was a report that stated JUN can act as an intermediate in antiviral immunity and TLR4 recognizes bacterial ligands to constrain the ability of antiviral immunity which combine bacterial and viral infections." (PMID 31531018, 2019). "Also, viral infection itself may result in a greater susceptibility to virally induced-TN-C release and the consequential TLR4 dependent inflammation, with respiratory syncytial virus (RSV) having been previously shown to induce the upregulation of TLR4 in bronchial epithelial cells." (PMID 31497021, 2019). "Overall, we demonstrate novel strategies to harness the TLR4 pathway to improve PD-1 therapy during chronic viral infection." (PMID 30726291, 2019). "Here, we explore the role of toll-like receptor 4 (TLR4) in the induction of damaging inflammatory responses during acute viral infections." (PMID 30571771, 2018). "TLR-4 has previously been shown to be an important initiator of c-Fos signaling when cells are triggered by lipopolysaccharide (LPS) or viral infection." (PMID 30186773, 2018). "Studies with well-known TLR4 inhibitors convincingly show that dampening the excessive inflammatory response mitigates disease and promotes survival, highlighting the therapeutic potential of TLR4 inhibitors in viral infections." (PMID 30571771, 2018). "LPS treatment also induces the expression of lncRNA NEAT1, which has been shown to be activated in viral infections and is responsible for transcription of inflammatory cytokines through the TLR4 signaling pathway." (PMID 29147069, 2017).
viral infection (continued). "Where several studies describe the role of TLR4 during viral infection, as TLR4 is upregulated in response to CVB3 inoculation on the plasma membrane and contributes to its pathogenesis, the contribution of especially TLR3 and TLR5 is less founded." (PMID 27878326, 2017). "TLR4 has been shown to intervene in viral infection with respiratory syncytial virus (RSV) and mouse mammary tumor virus." (PMID 24643046, 2014). "Our experimental results confirm that TLR4 plays an important role in resistance to both bacterial and viral infections in the duck." (PMID 24025421, 2013). "P38 MAPK is a determinant of virus infection, which depends on MyD88 expression and Toll-like receptor 4 (TLR4) ligation, and the inhibition of p38 MAPK signaling significantly inhibits virus replication." (PMID 23731466, 2013). "Our experimental results indicate that TLR4 plays an important role in resistance to both bacterial and viral infections in the duck." (PMID 24025421, 2013). "The first indication that TLR4 was involved in the response to viral infection came from research on RSV and VSV." (PMID 22642811, 2012). "TLR4 responds to molecular signatures of microbial origin (i.e., LPS), but more recent evidence suggests that TLR4 can also be activated by viral infection." (PMID 21375734, 2011). "The findings regarding eritoran’s effectiveness in preclinical models indicate that TLR4 antagonism could serve as a valuable therapeutic strategy for managing the inflammatory responses associated with MVD and similar viral infections." (PMID 40333077, 2025). "A role for TLR4 in pathology of mouse models of viral infection could also be the result of LPS influx following gut epithelial barrier breakdown." (PMID 41218088, 2025). "Inside the cell, Toll-like Receptors (TLR3, TLR4, TLR7 in viral infection, or TLR4 in bacterial infection) determine (a) the release of danger-associated molecular patterns, (b) the activation of the inflammatory response, and (c) the activation of innate pathways." (PMID 38891025, 2024). "Resveratrol has been shown to enhance antigen presentation of peritoneal macrophages via the upregulation of CD86, MHCII, and TLR4 levels, suggesting its role as a pseudorabies virus vaccine-adjuvant therapy, aiding in the host protection against viral infection." (PMID 38674902, 2024). "The interaction between MEVC-B and TLR4 could potentially trigger TLR4 signalling networks, activating immune responses against viral infections." (PMID 39146295, 2024). "The current data thus suggests that systemic blockade of TLR4 may come to the cost of attenuated IFN-mediated immunity during early virus infection." (PMID 38034686, 2023). "Interestingly, it is found that CHIKV-E2 interacts with TLR4 during infection which is essential for efficient viral infection in host macrophages." (PMID 37153546, 2023). "Collectively, these data indicate that the inhibition of TLR4 might lead to reduced viral infection and induction of the p38, and JNK-MAPK pathways." (PMID 37153546, 2023). "An earlier report on the respiratory syncytial virus (RSV) describes that the functional TLR4 is an essential component to promote viral infection and the infection-induced inflammasome activation, vascular damage, T cell activation, B cell maturation and NK cell activation in mice model." (PMID 37153546, 2023). "TLR2 and TLR4 have both been found during infection by HCV and HCV/HIV-1 co-infection, indicating that the inhibitory effect of quercetin towards TLR2 and TLR4 could also apply during viral infections, lowering the inflammatory response of the patient." (PMID 37513186, 2023). "Genetic mutation in TLR4/TLR9 may alter the expression or function of encoded proteins and their association with susceptibility to viral infections has been reported in different populations." (PMID 36915050, 2023).
viral infection (continued). "The toll-like receptor (TLR) family is a major pattern recognition receptor (PRR) family that recognizes a wide range of bacteria and viruses, and the protein TLR4 is involved in the induction of host immune responses to bacterial, fungal, and viral infections." (PMID 37438783, 2023). "Predominantly, TLR7, TLR3, and TLR4 are involved in sensing viral infections." (PMID 37515084, 2023). "Therefore, the study depicts TLR4 as one of the possible receptors of the CHIKV-E2 protein to facilitate viral infection." (PMID 37153546, 2023). "Moreover, these cells can undergo RIPK3-dependent cell death upon treatment with lipopolysaccharide (LPS, TLR4 agonist), oxidized LDL (which is recognized by TLR4), or upon certain viral infections." (PMID 36240069, 2022). "Nonetheless, further research is needed to understand whether TLR4 activation has a protective or detrimental role in viral infection, and the relative role of TLR4 compared to other PRRs." (PMID 36246240, 2022). "TLR4 is an important activation pathway in the inflammatory response to viral infection." (PMID 36500406, 2022). "It is also possible that indirect effects of viral infection modulate TLR4 activation." (PMID 36246240, 2022). "Further studies in animal models are necessary to characterize whether viral infection-induced changes to the microbiome alter immune responses and TLR4 activation." (PMID 36246240, 2022). "Excess activation of TLR4 plays a role in the pathogenesis of viral diseases." (PMID 34564326, 2021). "Moreover, TLR4 is also important in the induction of the host immune response against infectious diseases such as bacterial, fungal and viral infections, and malaria." (PMID 33505220, 2021). "It cannot be excluded that GR and GA may prevent viral infection by blocking TLR4 and thus ACE2 expression." (PMID 34201172, 2021). "Nevertheless, these observations suggest that TLR4 might play an important role in virus sensing during neurotropic viral infections, possibly through direct sensing of viral proteins through microglia and indirect sensing of danger signals via astrocytes." (PMID 34696494, 2021). "Treatment with TLR4 antagonists has been used successfully during other viral infections." (PMID 34564326, 2021). "Prior exposure to bacterial or viral infection could indeed upregulate TLR4 expression in circulating immune cells, contributing to an altered immune background, which could facilitate the development of GBS." (PMID 33752705, 2021). "Thus, TLR4 appears to have 2 pathway arms whose balance is dysregulated in viral infections: one predominantly proinflammatory that exacerbates myocarditis (MyD88 dependent) and the other anti-inflammatory and anti-viral (MyD88 independent)." (PMID 33505220, 2021). "Firstly, the question arises as to whether TLR4 activation is beneficial or harmful to the body during an acute viral infection." (PMID 33505220, 2021). "Previous studies have associated sequence variants in genes coding for the innate immune proteins Toll-like receptor 4 (TLR4), mannose-binding lectin (MBL), and interleukin-1 receptor antagonist (IL-1Ra) to increased risk for either bacterial or viral infection during cancer therapy." (PMID 33339376, 2020). "As a result, we hypothesized that JUN, VEGFA, TNFSF10, and TLR4 in PBMC can also regulate virus infection of HCC patients." (PMID 31531018, 2019). "However, the roles of TLR4 have been explored in recent decades in terms of viral infection, especially flaviviridae (Flavivirus; Dengue and Zika virus and Hepecivirus; HCV)." (PMID 30765614, 2019). "In the present study, we investigated whether TLR4 triggering could improve PD-1 therapy during a chronic viral infection." (PMID 30726291, 2019). "In conclusion, activation of TLR4 seems to play a nuanced role during viral infection." (PMID 30571771, 2018). "Is TLR4 activation during acute viral infections beneficial or harmful?" (PMID 30571771, 2018).